FGG (fibrinogen gamma chain)
Diseases named in the same sentence as FGG in open-access papers (continued):
Sharing a sentence is not in itself a finding about the gene and the disease.
liver disease (4 papers, 2016 to 2024). "The levels of fibrinogens (e.g., FGL1 and FGG) are increased in most patients with severe liver disease." (PMID 31998436, 2020). "In addition, many novel liver disease biomarkers were discovered, such as EGF-containing fibulin-like extracellular matrix protein 1 (EFEMP1), SAA2, CPN2, ANPEP, TGFBI, and FGG." (PMID 37209815, 2023).
lung carcinoma (4 papers, 2013 to 2024). "The first panel, consisting of FGB, FGG, and VWF proteins, exhibits promise as a diagnostic tool for the early detection of lung cancer." (PMID 37953280, 2023). "FGA, FGB, FGG and FGL1 were downregulated during EMT of lung cancer and were mapped to the GO term ‘Fibrinogen complex’." (PMID 24093963, 2013). "Although the current evidence can not support the regulation relationships between CSMD1 and FGG, it has been reported that the expression of FGG changed during EMT of lung cancer by several genes such as FOXA1 knockdown in A549 cells." (PMID 28959347, 2017).
ovarian carcinoma (4 papers, 2019 to 2024). A malignant neoplasm originating from the surface ovarian epithelium. "Zhang and colleagues identified LBP (lipopolysaccharide-binding protein), GSN (gelsolin), FGA (fibrinogen alpha chain), and FGG (fibrinogen gamma chain) as potential diagnostic exosomal proteins for ovarian cancer, with FGA found to be the most promising diagnostic marker." (PMID 34571921, 2021). "Among them, plasma exosomal FGG was recently found with fibrinogen β chain as a protein marker discriminating benign from malignant pulmonary nodules, being a promising prognostic biomarker for ovarian cancer or cardiovascular disease." (PMID 34063765, 2021).
bladder cancer (3 papers, 2015 to 2025). "FGG plays a critical role in coagulation, inflammation, and carcinogenesis and has been proposed as a potential diagnostic marker in various diseases, including non-small-cell lung cancer and bladder cancer." (PMID 40868977, 2025). "Two forms of fibrinogen, fibrinogen beta chain (FBB) and fibrinogen gamma chain (FGG), were also upregulated in the samples of bladder cancer patients in this study." (PMID 37371512, 2023). "Some of the proteins such as SERPINA1, FGG, FGA, APOA1 and HP were also found with differential abundance in urine in proteomics studies of bladder cancer, and TYMP in tissue in renal cell carcinoma, but mostly with opposite abundance level compared to our study." (PMID 25653573, 2015).
breast carcinoma (3 papers, 2023 to 2024). "Downregulation of the fibrinogen gamma chain has been associated with reduced resistance to anthracycline chemotherapy in breast cancer, and silencing of this chain has been shown to markedly increase apoptosis and reduce the proliferation, invasion, and migration of cancer cells." (PMID 39204193, 2024). "FGG was found to bind various integrin receptors to regulate tumor metastasis in colorectal and breast cancer models." (PMID 39227068, 2024). "In a study on anthracycline chemotherapy resistance in breast cancer, it was found that elevated levels of FGG were involved, promoting the survival and proliferation of breast cancer cells." (PMID 39227068, 2024). "The expression data of ECM fiber-encoding genes (e.g., COL1A1, COL1A2, FGA, FGB, FGG, ELN, FN1, and VTN) from 1358 patients with breast cancer were used for Kaplan–Meier overall survival analysis." (PMID 37369642, 2023).
Stroke (3 papers, 2009 to 2023). Sudden impairment of blood flow to a part of the brain due to occlusion or rupture of an artery to the brain. "Although FTL was more expressed than AHSG, TTR, and FGG using gene expression data for normal human tissues, it remains debatable whether iron itself and iron accumulation were beneficial or harmful after experimental stroke." (PMID 34168538, 2021).
cognitive decline (2 papers, 2014 to 2021). "Furthermore, FCN2 and FGG were related to brain atrophy and rate of cognitive decline." (PMID 34366831, 2021).
coronary artery disease (2 papers, 2010 to 2022). "In the present study we used a tagSNP approach to evaluate the role of genetic variation across FGA, FGB and FGG genes in the occurrence of coronary artery disease in a homogeneous Greek population sample of 305 patients and 305 controls." (PMID 20167083, 2010).
depression (2 papers, 2014 to 2021). "By studying the differentially expressed proteins of the exogenous coagulation pathway in the plasma samples of depression patients, we found that FGA, FGB, FGG and FVII in the EC pathway have all changed significantly." (PMID 34488523, 2021). "In conclusion, we screened 4 DEPs (FGA, FGB, FGG and FVII) in the EC pathway from depression patients’ plasma and provided potential biomarkers for the diagnosis of depression." (PMID 34488523, 2021). "The levels of fibrinogen beta chain (FIBB), fibrinogen gamma chain (FIBG), retinoic acid receptor beta (RARB), glutathione peroxidase 1 (GPX1), SH3 domain-containing protein 19 (SH319), and T-complex protein 1 subunit beta (TCPB) were lower in patients with major depression than in healthy controls." (PMID 24383611, 2014).
diabetes (2 papers, 2021 to 2023). "Our results indicated that after bariatric surgery the abundance in two isoforms of FGG and one isoform of FGB increased in the control and remission groups, but not in the patients with persistent diabetes." (PMID 34501327, 2021). "Regarding differences among the non-diabetic, diabetes remission, and persistent diabetes groups, considering the samples obtained before and after surgery as a whole, we found different abundances in nine spots from five proteins: CP, SERPINA1, ITIH4, plasminogen (PLG), and FGG." (PMID 34501327, 2021).
endometriosis (2 papers, 2016 to 2017). The growth of functional endometrial tissue in anatomic sites outside the uterine body. "Notably, the top genes associated with Stage B endometriosis in these pathways include FN1, FGG and FGA which are also part of the Reactome integrin linkage to MAPK pathways associated with all endometriosis." (PMID 28333195, 2017). "Notably, this includes FN1, FGG and FGA, which are also part of the Reactome MAPK-related pathways associated with all endometriosis." (PMID 28333195, 2017).
glaucoma (2 papers, 2017 to 2024). Increased pressure in the eyeball due to obstruction of the outflow of aqueous humor. "In agreement with our results, the downregulation of FGA (fibrinogen alpha chain), FGG (fibrinogen gamma chain), and HBB (hemoglobin subunit beta) was assessed in primary open-angle glaucoma patients’ aqueous humor." (PMID 39000104, 2024).
hypodysfibrinogenemia (2 papers, 2024). "Here we present a family with congenital hypodysfibrinogenemia associated with a novel FGG gene mutation, and we report on the performance of global hemostasis assays in elucidating the clinical phenotype." (PMID 39473893, 2024). "We report on a family with hypodysfibrinogenemia and a novel FGG heterozygous missense mutation, possibly leading to conformational changes or covalent dimerization." (PMID 39473893, 2024). "Our study reported 3 patients with hypodysfibrinogenemia from the same family who had 3 compound missense mutations in the FGA, FGB, and FGG genes." (PMID 38953055, 2024).
insomnia (2 papers, 2021 to 2022). A sleep disorder characterized by difficulty in falling asleep and/or remaining asleep. "Among them, the expression of F2, HP, FGA, FGB, FGG, and ApoB were upregulated in insomnia patients with wakefulness, and A2M, AHSG, APP, and ApoA1 were downregulated." (PMID 33511209, 2021). "Among them, HP, MMP9, FGA, FGB, and FGG were validated as upregulated, and APP, AHSG, and IGF1 were downregulated in patients with insomnia." (PMID 35958162, 2022). "In the results, HP, FGA, FGG, FGB, and MMP9 were upregulated in patients with insomnia, and FN1, APP, EGF, AHSG, and IGF1 were downregulated compared with controls." (PMID 35958162, 2022). "On the other hand, through Western blot experiments, we verified that the expression of FGG, FGB, FGA, APOB, F2, and HP was upregulated in insomnia patients with wakefulness compared with the control, while the expression of A2M, AHSG, and APOA1 was downregulated." (PMID 33511209, 2021).
liver cirrhosis (2 papers, 2024 to 2025). "Additionally, another six genes (ALB, APOH, FABP1, FGB, FGG, and TF) were identified from our previous HCC EV-specific gene panel given their performance in distinguishing early-stage HCC from liver cirrhosis." (PMID 40307890, 2025).
pancreatic cancer (2 papers, 2023). "Additionally, FGG is thought to distinguish cancer from normal sera as a potential tumor marker in pancreatic cancer." (PMID 37841237, 2023). "In addition, FGG was found to be overexpressed in the tissues and blood of hepatocellular and pancreatic cancer patients." (PMID 37350944, 2023).
preeclampsia (2 papers, 2013 to 2025). Preeclampsia is a hypertensive disorder of pregnancy that is characterized by new-onset hypertension with proteinuria presenting after 20 weeks of gestation, and depending on mild or severe forms may initially present with severe headache, visual disturbances, and hyperreflexia. "RT‒qPCR analysis confirmed the upregulation of FKBP5, LAMA5, FZD5 and FGG mRNA expression in preeclampsia." (PMID 40490753, 2025). "Interestingly, in a LC-MS/MS proteomics screen of the SCOPE collection of preeclampsia maternal blood samples taken at 20 weeks, increased fibrinogen gamma chain expression provided one of two strong predictors of subsequent development of preeclampsia." (PMID 23469002, 2013).
pulmonary fibrosis (2 papers, 2021 to 2023). Chronic progressive interstitial lung disorder characterized by the replacement of the lung tissue by connective tissue, leading to progressive dyspnea, respiratory failure, or right heart failure. "For example, in a rat pulmonary fibrosis model, FGG was highly expressed in fibrotic lung tissue." (PMID 37124494, 2023).
staphylococcus aureus infection (2 papers, 2023 to 2024). An infectious process in which the bacteria Staphylococcus aureus is present. "In this study, five important human genes (KRT10, FGG, TLR4, CD14, and MD2) reported in the development and spread of pertussis and staphylococcus aureus infections." (PMID 37169818, 2023). "For instance, Staphylococcus aureus infection (bta05150) pathway was significantly enriched by genes (e.g., CATHL2, CATHL3, KRT18, FGG) harboring DMCs at their first exons as well as differential genes (identified by MethGET) having significant DNA methylation changes in their regulatory regions." (PMID 38486242, 2024).
amyloid (1 paper, 2018). "Notably, one protein; fibrinogen gamma chain (FGG), when combined with age was able to predict neocortical amyloid burden with 59% sensitivity and 78% specificity." (PMID 30618716, 2018).
Arthritis (1 paper, 2019). Inflammation of a joint. "Taken together, we found that several proteins with inflammatory function were decreased in arthritis CSF after infliximab treatment, including proteins with additional neuro-immunomodulatory function such as FGG, CNTN1 and CADM3." (PMID 30770760, 2019). "Several immune-related proteins in the CSF of arthritis patients decreased during TNF blockade, including FGG and CFB that both correlated strongly with systemic inflammation." (PMID 30770760, 2019).
autoimmune disease (1 paper, 2021). A disorder resulting from loss of function or tissue destruction of an organ or multiple organs, arising from humoral or cellular immune responses of the individual to their own tissue constituents. "SERPING1, C3, FGA, FGG, and CFH were significantly related to autoimmune diseases, and C3 in particular is associated with systemic lupus erythematosus (SLE) that shows a similar immunopathogenic basis to pSS." (PMID 34516718, 2021).
cervical cancer (1 paper, 2023). A primary or metastatic malignant neoplasm involving the cervix. "The results showed that high expression of MYH1, MYH4, FGG, and DEPP1 was associated with shorter overall survival of patients with cervical cancer; high expression of SULT1E1, RAB3C, CXCR3, and PROX2 was associated with longer overall survival of patients with cervical cancer." (PMID 37350944, 2023). "High expression of MYH1, MYH4, FGG, DEPP1, and ZBTB16 was associated with shorter overall survival of patients with cervical cancer; high expression of SULT1E1, RAB3C, CXCR3, and PROX2 was associated with longer overall survival of patients with cervical cancer." (PMID 37350944, 2023). "Our results showed that FGG was downregulated in the tumor tissues after PKU12 + siRNA treatment, and FGG may predict poor prognosis in patients with cervical cancer, suggesting that knockdown of HPV16 oncoproteins may inhibit FGG expression in cervical cancer." (PMID 37350944, 2023). "However, the role of FGG in cervical cancer has not been studied." (PMID 37350944, 2023).
chronic kidney disease (1 paper, 2025). Impairment of the renal function secondary to chronic kidney damage persisting for three or more months. "We identified the hub genes of CKD (Fn, Timp1, C3, Apoe, Trf, Fbn1, FGG, Penk, Ckap4, and Gpc3) through multiple bioinformatics analyses and successfully verified their expression in a mouse chronic kidney disease model." (PMID 40564035, 2025).
colorectal cancer (1 paper, 2023). A primary or metastatic malignant neoplasm that affects the colon or rectum. "Moreover, high expression of FGB and FGG in tumor tissue has been associated with a poorer prognosis in patients with gastric, prostate, liver, and colorectal cancers." (PMID 37953280, 2023).
Encephalopathy (1 paper, 2018). Encephalopathy is a term that means brain disease, damage, or malfunction. "Loss of function mutations in FGG have been associated with fibrinogen deficiency, while the c.1423G > A mutation in TBCD causes a novel syndrome of neurodegeneration and early onset encephalopathy." (PMID 29769041, 2018).
endometritis (1 paper, 2023). An acute or chronic, usually bacterial infectious process affecting the endometrium. "In our study, the level of FGG transcripts decreased in the liver of the castrated bucks that were administered a mixture of dried extracts from R. officinalis and C. longa, while high levels of FGB and FGG were found in cattle liver, wherein their expression increased during endometritis." (PMID 37895281, 2023).
endothelial dysfunction (1 paper, 2021). In vascular diseases, endothelial dysfunction is a systemic pathological state of the endothelium (the inner lining of blood vessels) and can be broadly defined as an imbalance between vasodilating and vasoconstricting substances produced by (or acting on) the endothelium. "From the 14 upregulated exosomal proteins, FBG, FGG, ITIH4, and SERPINA3 coding gene for alpha-1-antichymotrypsin were associated to endothelial dysfunction and coagulation cascade activation and platelet degranulation." (PMID 33535467, 2021).
epilepsy (1 paper, 2020). A brain disorder characterized by episodes of abnormally increased neuronal discharge resulting in transient episodes of sensory or motor neurological dysfunction, or psychic dysfunction. "Fibrinogen (FGG, FGA) was also found to be increased in the plasma of patients with epilepsy." (PMID 33082886, 2020).
femoral head osteonecrosis (1 paper, 2024). "Scientific investigation has indicated that fibrinogen gamma chain (FGG) could also have a role in cartilage degradation, acting in a manner similar to that of femoral head osteonecrosis." (PMID 39596473, 2024).
fibrosis (1 paper, 2023). the formation of excess fibrous connective tissue in an organ or tissue in a reparative or reactive process. "Top novel candidate genes with high entropy values include VTN, FGB and FGG, which are associated with changes observed in fibrosis under chronic liver damage condition." (PMID 36944690, 2023).
head and neck cancer (1 paper, 2024). A primary or metastatic malignant neoplasm affecting the head and neck. "However, FGG dysregulation is known as a marker of radioresistance in head and neck cancer, which is also an HPV-related cancer." (PMID 39262965, 2024).
hemophilia A (1 paper, 2021). The most common form of hemophilia characterized by spontaneous or prolonged hemorrhages due to factor VIII deficiency. "In severe cases, although hemophilia A was combined with other bleeding factor deficiencies, the genetic alterations in the second gene (FGB or FGG (P29, P30, P31), F9 (P28)) did not change the severity of the bleeding episodes." (PMID 33477601, 2021).
injury (1 paper, 2021). Damage inflicted on the body as the direct or indirect result of an external force, with or without disruption of structural continuity. "In terms of interaction with serious complications in COVID‐19 patients, 6 markers (MFAP4, ECM1, CDKN2B.AS1, CAPN2, FGG, and CD147) and 2 exRNAs (SNORD33 and miR‐122‐5p) are involved in thrombosis or liver injury." (PMID 34122778, 2021).
ischemia (1 paper, 2023). A hypoperfusion of the BLOOD through an organ or tissue caused by a PATHOLOGIC CONSTRICTION or obstruction of its BLOOD VESSELS, or an absence of BLOOD CIRCULATION. "FGB and FGG are fibrinogen chains that could increase with increased retinal vascular permeability due to ischemia or inflammation." (PMID 36674802, 2023).
liver failure (1 paper, 2021). A liver disease characterized by the liver losing or has lost all of its function. "A few fibrinogen mutations, clustered in exons 8 and 9 of FGG, cause fibrinogen deposit in endoplasmic reticulum, which in turn can give rise to liver failure." (PMID 33668986, 2021).
lung adenocarcinoma (1 paper, 2021). A carcinoma that arises from the lung and is characterized by the presence of malignant glandular epithelial cells. "The expression of NTS was highly correlated with that of CPS1, fibrinogen gamma (FGG), and glutathione peroxidase 2 (GPX2) in a subgroup of lung adenocarcinoma samples, suggesting these genes might belong to a gene coexpression network." (PMID 33493519, 2021).
lung squamous cell carcinoma (1 paper, 2025). "Moreover, silencing FGG in lung squamous cell carcinoma (LUSC) tissue notably altered the extent of immune infiltration, particularly affecting the infiltration of M1-type macrophages derived from THP-1 cell polarization." (PMID 41200166, 2025).
mastitis (1 paper, 2014). Inflammation of breast tissue during lactation or postpartum due to an obstructed duct or infection. "Two proteins FGG and HP upregulated by 16.75- and 5.45- fold in mastitis-infected cow’s tissues were involved in S. aureus infection pathway." (PMID 25273983, 2014).
myopia (1 paper, 2023). "Antithrombin-III (SERPINC1), fibrinogen gamma chain (FGG), and fibrinogen beta chain (FGB) are potential novel biomarkers for myopia." (PMID 36674802, 2023).
nasal polyp (1 paper, 2021). "Coagulation proteins FGA, FGB, FGG, and fibronectin (FN1) were all also abundant in nasal polyp biopsies in this study." (PMID 33220024, 2021).
Obesity (1 paper, 2024). Accumulation of substantial excess body fat. "Protein abundance of FB and FGG were reported to be increased in several tissues, including EVs, platelets and SKM, of patients with obesity compared to lean individuals in three independent studies." (PMID 38703299, 2024).
pertussis (1 paper, 2023). A contagious bacterial respiratory infection caused by Bordetella pertussis. "We also predicted the most effective cores for siRNAs to affect staphylococcus aureus (ClfB, IsdA, sdrC, sdrD, and SasG) and pertussis (PtxE, PagP, PtxD, PtxC, PtxA, and PtxB) bacterial genes that interacted with human KRT10, FGG, and TLR4 genes." (PMID 37169818, 2023).